TNF (tumor necrosis factor)
Diseases named in the same sentence as TNF in open-access papers (continued):
Sharing a sentence is not in itself a finding about the gene and the disease.
endotoxemia (continued). "On one hand AnxA1 or peptide Ac2-26 treatment, in the case of LPS-induced endotoxemia, inhibited TNF-α release, whereas in the absence of AnxA1, increased levels of the cytokine was observed." (PMID 23497133, 2013). "Production by macrophages and other immune cells of the key pro-inflammatory cytokines(including the tumor necrosis factor α (TNF-α), the major mediator of septic shock(endotoxemia) that is induced by the action of LPS) plays a significant role in overcominginfectious diseases." (PMID 23150803, 2012). "Although HMGB1 is a well-known mediator of endotoxemia and a proinflammatory cytokine-like protein in vivo, purified recombinant HMGB1 only has weak in vitro proinflammatory activity, such as the induction of TNF-α production." (PMID 21660935, 2011). "Our results showed that the mRNA and protein levels of TNF-α in rmMFG-E8 treated WT mice were significantly reduced as compared to non-treated mice with endotoxemia." (PMID 22114683, 2011). "HPep1 inhibited LPS binding to LBP and LPS-mediated TNF-α production in human PBMCs and mice with subclinical endotoxemia, although it is not a lipid A-binding peptide." (PMID 21660935, 2011). "Now it has been shown that vagus nerve stimulation fails to inhibit TNF production in splenectomized animals during lethal endotoxemia." (PMID 20628562, 2010). "abortus induced a modest increase in cytokines and mild signs of endotoxemia, but not lethality, probably due to the lower levels of TNF-α generated." (PMID 17637846, 2007). "In endotoxemia, the severe lung injury observed in neutropenic rats does not depend on TNF-α or MIP-2 produced in the lung." (PMID 17397554, 2007). "In early endotoxemia, the more severe lung injury observed in neutropenic compared to non-neutropenic rats does not depend on TNF-α, IL-1β and MIP-2 in the lung." (PMID 17397554, 2007). "In an endotoxemia model, pulmonary mRNA and protein concentration of TNF-α were similar in both neutropenic and non-neutropenic mice." (PMID 17397554, 2007). "Nevertheless, TNF-α was not increased at 12h, instead, peaked at 18 h when is the start time of endotoxemia." (PMID 23674977, 2006). "In addition, ANC alleviated endotoxemia as well as decreased NOX4 and TNFα overexpression along with JNK phosphorylation, indicating that it could alleviate the inflammatory and pro-oxidant conditions stimulated by extra fat uptake." (PMID 41585869, 2025). "Endotoxemia activates a signaling cascade in which LPS binds to toll like receptor 4 (TLR4) complex, activating the Toll-like receptor 4 (TLR4) and stimulating NF-κB to produce inflammatory cytokines such as tumor necrosis factor-α (TNF-α) and interleukin-1β (IL-1β)." (PMID 40004236, 2025). "Other studies, on the other hand, have demonstrated that the gp91phox subunit of NADPH oxidase would have a further effect in the induction of cardiac depression resulting from endotoxemia, mediated by the expression of TNF-α, which in turn exerts a negative inotropic effect." (PMID 38474158, 2024). "Considering the primary role of TNF-α in modulating the expression of IL-1β and IL-6, we hypothesized that TNF-α may have a more immediate role in systemic inflammation and organ injury (e.g., the lungs) in endotoxemia." (PMID 35337084, 2022). "We assessed the therapeutic efficacy between triple cytokine (tumor necrosis factor-α [TNF-α], interleukin-1β [IL-1β], and IL-6) inhibition (mediated by KCF18 peptide) and single cytokine (TNF-α) inhibition (mediated by SEM18 peptide) on alleviating lung injury in the early phase of endotoxemia." (PMID 35337084, 2022). "Interestingly, using a murine LPS-induced endotoxemia model showed that only the TEGOH-coated gold nanoparticles showed the similar suppression of TNF-α production, whereas the hydrophobic ZDiPen failed to recapitulate the cytokine response." (PMID 32849612, 2020). "U/S stimulation did not suppress TNF levels during endotoxemia in α7nAChR KO mice." (PMID 30862827, 2019).
endotoxemia (continued). "Interestingly, animal model studies suggest that administration of insulin-like growth factor I (IGF-1) in cirrhotic rats can effectively downregulate the expression of tumor necrosis factor alpha (TNF-α) and decisively reduce portal vein pressure, bacterial translocation, and endotoxemia." (PMID 30930689, 2019). "A main observation of this study is that SIRT2 deficiency protected mice from chronic staphylococcal infection, while it neither protected nor sensitized mice to TNF-induced shock, endotoxemia, rapidly lethal E. coli peritonitis and mild K. pneumoniae pneumonia." (PMID 28894448, 2017). "The anti-inflammatory effect of glucocorticoids in septic systemic inflammation is well documented, and in a previous experimental study of ours, we concluded that steroid treatment prior to endotoxemia had beneficial circulatory effects, which were not mediated by TNF-alpha, IL-6, or NO." (PMID 28101752, 2017). "Our data further suggest that the development of anti- endotoxemia therapy concurring to induce SHP-1 activity could represent a new avenue to consider, as actual therapies mainly focusing at specifically blocking TNF-α and other pro-inflammatory cytokines showed limited successes." (PMID 28533521, 2017). "However, it warrants further studies to demonstrate whether the production and release of TNF-α, IL-1βand IL-6 is altered in HMGB1/TLR4 signaling pathway and whether this is the main pathological mechanism in endotoxemia induced acute neuro-inflammation." (PMID 28059131, 2017). "Therefore, we hypothesize that sesamol increases IL-10, decreases the production of TNF- and IL-1β to balance the SIR against LPS-induced hypotension and endotoxemia." (PMID 26839527, 2015). "Furthermore, analysis of plasma TNF and MIP-2 levels revealed a very similar outcome: used in a concert, NO-donor and Ab/SOD afforded significantly more potent suppression of cytokine level in blood in response to endotoxemia (respectively)." (PMID 24146950, 2013). "Also, we found that exercised diabetic rats had lower inflammatory response during endotoxemia as well as a negative correlation between lavage TNF-α level and the HSP72 level in the lungs." (PMID 24392457, 2013). "Both HPep1 and HPep6 inhibited LPS-induced TNF-α release in human peripheral blood mononuclear cells (PBMCs) and also decreased serum levels of TNF-α in a mouse model of subclinical endotoxemia, suggesting that these two LPS-binding peptides may have potential as antiseptic therapeutics." (PMID 21660935, 2011). "This difference could be responsible for the protective effect of the lactic acid bacterium since IL-10 inhibits the synthesis of pro-inflammatory cytokines such as TNF-α and IL-1 in vitro and attenuate the increase in PAI-1 concentrations during human endotoxemia." (PMID 19835595, 2009). "In our study, endotoxemia did not lead to the TNF-α production in the lung." (PMID 17397554, 2007). "Neutrophils may regulate TNF-α and MIP-2 production in endotoxemia." (PMID 17397554, 2007). "Considering that TNF-α, IL-1β, and IL-6 as well as their bindings to the cognate receptors play crucial roles in mediating the development of endotoxemia-induced organ injury, we hypothesized that KCF18 can alleviate acute liver injury in mice with endotoxemia." (PMID 34065201, 2021). "Furthermore, our data confirmed that endotoxemia increased the plasma levels of the pro-inflammatory cytokine IL-6 in plasma and the TNF-α renal expression in wild type MORG1+/+ mice while in contrast IL-6 and TNF-α induction were significantly reduced in MORG1+/− mice." (PMID 29402223, 2018). "We noticed that clonidine, even though not as effective as GBZ in rescuing viability, could mildly reduce TNF-α secretion, potentially by reducing the systemic distribution of LPS and cytokines, further suggesting that the hypotensive activity of GBZ could also contribute to endotoxemia reduction." (PMID 28659918, 2017).
endotoxemia (continued). "SIRT1 inhibited LPS- or TNF-α-induced HMGB1 release from macrophages by directly interacting with HMGB1 in an acetylation-dependent manner; therefore, we next analyzed whether SIRT1 affected the circulating HMGB1 level during endotoxemia, a standard model of systemic inflammation." (PMID 26522327, 2015). "Based on greater TNF and SAA during the dry off period it is speculated that the infection of the udder might have started immediately after drying off and cows of SCM group have been in a state of endotoxemia during the entire dry off period and immediately after calving." (PMID 26705479, 2015). "However, results of the current study collectively indicate that the hyperinflammatory state previously observed during endotoxemia in the aged may, in part, be due to the increase in Kupffer cell CD14 expression, leading to increased Sphk-1 and subsequent increases in TNF-α." (PMID 23817990, 2013). "For example, TNF-α concentrations found during experimental endotoxemia are much higher than in septic patients, whereas other cytokines are released to a lesser extent and some inflammatory mediators found in septic patients are not induced during experimental endotoxemia." (PMID 20444270, 2010). "Other previously reported immune phenotypes in MSM, such as increased frequencies of gut mucosal Th17 cells and IFN-γ+ TNF-α+ CD8+ T cells, increased endotoxemia, and lower blood CD4/CD8 ratios were either not observed or not measured in our cohort." (PMID 30947289, 2019). "Furthermore, in the LPS-induced endotoxemia model, which is not solely dependent on NLRP3 to elicit an inflammatory response, we observed that BI6727 treatment also reduced TNF-α levels." (PMID 37698938, 2023). "Moreover, TNF-α and MIP-2 levels are not dependent on C/EBPδ during pneumococcal meningitis, although these cytokines have been shown to be regulated by C/EBPδ during LPS-induced models of acute lung injury and endotoxemia." (PMID 25958220, 2015).
osteoarthritis (493 papers, 2005 to 2026). A noninflammatory degenerative joint disease occurring chiefly in older persons, characterized by degeneration of the articular cartilage, hypertrophy of bone at the margins and changes in the synovial membrane. "TNF-α was considered essential in the structural deterioration linked to the advancement of osteoarthritis." (PMID 40522441, 2025). "Chronic conditions such as osteoarthritis and cervical spondylosis elevate systemic IL-6 and TNF-α levels, both of which are implicated in neuropathic pain pathogenesis." (PMID 41393290, 2025). "Future research ought to incorporate experimental validation to delve deeper into the specific mechanisms of TNF signaling pathway-associated genes in osteoarthritis." (PMID 40826778, 2025). "Increased expression of TNF/TNF-α (tumor necrosis factor) is a predominant feature of osteoarthritis, causing inflammation and joint pain in patients." (PMID 40759632, 2025). "Specifically, active compounds in CHM have been shown to attenuate inflammation mediated by key cytokines, such as interleukin and tumor necrosis factor, both of which are critical in the pathogenesis of osteoarthritis-associated pain." (PMID 40861240, 2025). "Two main inflammatory cytokines linked to the progression of osteoarthritis are interleukin-1 (IL-1) and tumor necrosis factor alpha (TNFα)." (PMID 40647239, 2025). "Our previous work demonstrated that TNFα, a mediator implicated in articular diseases such as osteoarthritis (OA), downregulates Cx43 levels in chondrocytes through proteasome activation, impacting both gap junction numbers and nuclear Cx43 expression." (PMID 39126115, 2024). "On the other hand, shikimic acid works as a significant therapeutic agent in the treatment of osteoarthritis by halting the breakdown of type II collagen caused by tumor necrosis factor (TNF)." (PMID 37950334, 2023). "Based on WGCNA, we further revealed a set of genes associated with osteoarthritis and immune status, which were involved in the TNF signaling pathway, and IL-17 signaling pathway." (PMID 36681837, 2023). "Osteoarthritis is mentioned as an inflammatory process associated with active secretion of TNF-α and IL-1β." (PMID 37443993, 2023). "The immunological causes of osteoarthritis are known to involve various cytokines such as B cells, T cells, TNF-α, IL-1, IL-6, and IL-17, among others." (PMID 37623223, 2023). "The expression of this protein was associated with levels of inflammatory cytokines (IL-1β and TNF-α) in osteoarthritis." (PMID 37936684, 2023). "The TNF signaling pathway is associated with osteoarthritis activity and pathology, including bone loss, osteoblasts proliferation, and inflammation." (PMID 35281924, 2022). "Mg can reduce the loss of type II collagen and glycosaminoglycan in osteoarthritis, and can inhibit the expression of interleukin-1β (IL-1β), Tumor Necrosis Factor-α (TNF-α), and matrix metalloproteinase 13 (MMP13) in osteoarthritis." (PMID 36546928, 2022). "Levels of interleukin-6 (IL-6) and tumor necrosis factor-α (TNF-α), both key pro-inflammatory cytokines that induce cartilage catabolism, are elevated in OA patients (Chow and Chin, 2020; Osteoarthritis linked to higher parkinson’s disease risk, 2021)." (PMID 36419937, 2022). "Transient changes in cytokine levels involving inflammatory events associated with osteoarthritis have been observed in patients with OA, with effects being especially noted in the concentrations of interleukin 1 (IL-1) and tumor necrosis factor-α (TNF-α)." (PMID 33572416, 2021). "IL-10 decreases TNF-α production and TNF-α mediated events associated with osteoarthritis development, thereby suggesting the pathophysiological importance of a regulated anti- and pro-inflammatory cytokine balance on joint integrity." (PMID 33469085, 2021). "This is important since previous research has associated the elevated serum levels of TNF-α with severity of osteoarthritis and its future progression." (PMID 34940003, 2021).
osteoarthritis (continued). "Pro-inflammatory cytokines that cause the pathogenesis of degenerative joint diseases, including IL-1β, IL-6 and TNF-α, suppress the expression of these genes." (PMID 32030322, 2020). "Pro-inflammatory cytokines such as IL-6 and TNF-α levels are elevated in the synovial fluid and cartilage of patients with osteoarthritis and chronic elevations in cytokines are associated with an increased risk of osteoarthritis." (PMID 30871193, 2019). "Higher blood levels of C-reactive protein (CRP), IL-6, and TNF-α have been associated with an increased risk of osteoarthritis, dementia, sarcopenia, and aging." (PMID 29464019, 2018). "In the knee, both TNF-α and IL-6 have been associated with knee cartilage loss and elevated IL-6 is a predictor of radiographic osteoarthritis, suggesting a link between low-level inflammation and osteoarthritis pathogenesis." (PMID 30021590, 2018). "Several case–control studies have been conducted to clarify the association between the tumor necrosis factor alpha (TNF-α) -G308A polymorphism and risk of osteoarthritis (OA); however, the results are inconsistent." (PMID 25398219, 2014). "Furthermore, CRP, IL-6, and TNF-α were found to be reduced by resistance and neuromuscular training in osteoarthritis (OA) patients with pain caused by physical dysfunction." (PMID 41598488, 2026). "Indeed, TNF-α and IL-6 seem to be the mediators involved on the deleterious effect of vitamin D deficiency in osteoarthritis." (PMID 39940305, 2025). "Pro-inflammatory cytokines such as IL-1β, TNF-α, and IL-6, which are key compounds in the pathogenesis of osteoarthritis, may lead to the loss of articular cartilage homeostasis through metabolic changes and significantly accelerate joint injury." (PMID 37548663, 2024). "TNF-α, in combination with IL-1β, is recognized as a pivotal inflammatory cytokine implicated in the pathophysiological mechanisms observed during the progression of osteoarthritis." (PMID 39204123, 2024). "NLRP3 inflammasome has been implicated in osteoarthritis pathological progression through secreting proinflammatory cytokines including IL-1β and tumor necrosis factor-alpha (TNF-a), producing cartilage degrading enzymes like MMP3 and aggravating synovial membrane inflammation." (PMID 35935815, 2022). "PI3K/Akt pathway was associated with TNF-α-induced activation of fibroblast-like synoviocytes in OA, which may be involved in the pathogenesis of osteoarthritis." (PMID 31829201, 2019). "Interestingly, GPC6 seems to increase the risk of spinal osteoarthritis by causing osteoporosis, and osteoarthritis in the spine increases the levels of inflammatory cytokines such as IL‐1, and TNF‐a, which lead to homeostatic imbalance in disk matrix." (PMID 31111662, 2019). "Moreover, IL-1β and TNF-α induce activation of synovial fibroblasts and osteoclast cells that are associated with chronic inflammation and bone loss in osteoarthritis." (PMID 28036032, 2016). "Additionally, a number of proinflammatory cytokines have been implicated in the pathogenesis of osteoarthritis, including IL-6, IL-17, and TNFα." (PMID 20604941, 2010). "Additionally, TNF-α cannot directly cause extracellular matrix degradation in osteoarthritis chondrocytes but rather induces chondrocyte production of MMP3 through TNF-α receptor P55, leading to degradation of the cartilage matrix and subsequent chondrocyte apoptosis." (PMID 37953787, 2023). "Similarly, IL-1β, IL-8, and TNFα serum levels have been associated with osteoarthritis (OA)." (PMID 37445700, 2023). "Down-regulates MMP3 and TNF-a genes; reduces the loss of cell matrix of rat chondrocytes; maintains cell activity; down-regulates the expression of genes related to cell inflammation; reduces inflammation; and exerts a certain therapeutic effect on osteoarthritis in vitro." (PMID 35566359, 2022).